IL6 (interleukin 6)
Diseases named in the same sentence as IL6 in open-access papers (continued):
Sharing a sentence is not in itself a finding about the gene and the disease.
COVID-19 (continued). "Multiple studies have demonstrated that IL-6 levels are elevated in patients who suffer from a severe form of COVID-19." (PMID 35806986, 2022). "The top six anti-COVID-19 core targets, IL-6, PPARG, MAPK3, PTGS2, ICAM1, and MAPK1, were molecularly docked with the three key active phytomolecules of Kochiae Fructus." (PMID 35992697, 2022). "The course of COVID-19 includes the inflammatory cytokine storm, acute respiratory distress, and multiorgan failure with elevated levels of IL-6, D-dimer, serum ferritin, and C-reactive protein (CRP)." (PMID 36359290, 2022). "In particular, COVID-19 patients with high levels of IL-6 have been observed to have a worse prognosis." (PMID 36296527, 2022). "Many of the upregulated genes annotated in the Coronavirus pathogenesis pathway, such as IL6 and CCL2, are associated with hypercytokinemia or cytokine storm, a systemic hyper-inflammatory state that has been shown to influence COVID-19 disease severity." (PMID 35945487, 2022). "A retrospective study in patients admitted to the intensive care unit (ICU) with confirmed COVID-19 showed highly elevated levels of IL-6 and delayed cytotoxic immune responses, which are characteristics of severe COVID-19-induced ARDS." (PMID 35563199, 2022). "The strong inflammatory component of COVID-19 has led to interest in measuring cytokines such as IL-6, as well as other differentially expressed biomarkers, but these assays are not routinely available in clinical laboratories." (PMID 35741134, 2022). "IL-6 is elevated in patients with COVID-19 and is positively correlated with the severity of COVID-19 symptoms." (PMID 35281455, 2022). "Elevated levels of IL-6 in hospitalized patients with COVID-19 are directly correlated with high levels of cTn." (PMID 35888173, 2022). "Interleukin-1a is one of the initial cytokines released in COVID-19, inducing IL-6, TNF-α, granulocyte-macrophage colony stimulating factor (GM-CSF), and IL-17 expression after binding to its receptor." (PMID 36422492, 2022). "IL-6 is associated with different diseases and viral infections, including COVID-19, where the median concentration of IL-6 gradually increases from 1.5 pg/mL to 21.55 pg/mL depending on the severity of inflammatory symptoms." (PMID 35337143, 2022). "Elevated IL-6 levels were correlated with excessive immune response, hyperinflammation, and poor prognosis in COVID-19 patients." (PMID 36366457, 2022). "COVID-19 patients in hospitalisation treated with low-molecular-weight heparin were found to have reduced levels of IL-6 with a simultaneous increase in lymphocytes." (PMID 35742845, 2022). "Although we cannot provide direct evidence that Tocilizumab treatment is useful in patients with COVID-19 and lymphomas, our results confirm that IL-6 plays a role in the COVID-19 disease and anti-cytokine treatment should be further explored." (PMID 36579547, 2022). "For instance, IL-6 levels were shown to correlate with clinical disease severity in COVID-19 and IL-6 receptor antagonists were shown to improve outcomes including survival in critically ill patients." (PMID 35786403, 2022). "(ii) Baseline factors such as patient age, disease severity, and IL-6 are early predictors of clinical outcomes among COVID-19 patients." (PMID 35248063, 2022). "In this case, high levels of interleukin 6 (IL-6), procalcitonin, and troponin I support this thesis of maintaining inflammatory setting even in afebrile COVID-19 patients." (PMID 35448072, 2022). "COVID-19 patients with DM have significantly higher inflammatory markers, such as interleukin 6 (IL-6), C-reactive protein (CRP), and neutrophil–lymphocyte ratio (NLR) than those without DM." (PMID 36292550, 2022). "Hypertensive disorders of pregnancy and COVID-19 share an exaggerated inflammatory response, guided by cytokines such as IL-6, TNF-α and IFN-γ leading to endothelial damage." (PMID 36471262, 2022).
COVID-19 (continued). "Elevated serum concentrations of some inflammatory mediators have been described in patients with severe COVID-19, in particular, cytokines such as IL-1 and IL-6." (PMID 35597911, 2022). "In the serum of most COVID-19 patients, the levels of proinflammatory cytokines, including IL-1β, IL-2, IL-6, IL-8, IL-17, G/GM-CSF, MCP1, CCL3 and TNF, are significantly elevated, which is considered a cytokine storm." (PMID 35450063, 2022). "Elevated IL-6 production by individuals with prediabetes was found to correlate with important parameters of severe COVID-19, such as LDH, CRP, and low O2 saturation." (PMID 35898449, 2022). "Even at 8 months after viral infection, inflammatory biomarkers such as IL-6, interferon-β, and interferon-λ2/3 remain persistently high in COVID-19 survivors." (PMID 35248063, 2022). "Elevated serum levels of IL-6, IL-8, IL-1β, and TNF-α correlate with moderate and severe COVID-19, while IL-12p70 and IL-2 serum expression is associated with asymptomatic and mild diseases." (PMID 36526691, 2022). "The results of this meta-analysis were also in line with a previous meta-analysis of RCTs that presented a reduction in the incidence of intubation in COVID-19 patients receiving IL-6 inhibitors." (PMID 35215138, 2022). "Joint models for the analysis of repeated measurements of PCT, suPAR, and IL-6 are a useful method for predicting mortality in COVID-19 patients in the ICU." (PMID 35859926, 2022). "The main factor causing CRP generation and high levels of IL-6, which are connected to liver damage in COVID-19, is IL-6 generated by T cells, macrophages, and monocytes in response to the activation of the inborn and adaptive immune systems." (PMID 35928369, 2022). "For instance, the level of the proinflammatory cytokine IL-6 was decreased in the plasma of patients with acute COVID-19 from the first to the third week." (PMID 36081516, 2022). "As previously reported, IL-6 was higher in severe and moderate COVID-19 patients than healthy and mild COVID-19 subjects (p < 0.001)." (PMID 35508575, 2022). "A cytokine storm in Coronavirus-disease-19 (COVID-19) is accompanied by the rapid release of pro-inflammatory cytokines IL-6 and TNF-α." (PMID 35651623, 2022). "Due to certain similarities between COVID-19 and RA, some treatments used to treat COVID-19 patients have been borrowed from rheumatologists: hydroxychloroquine, glucocorticoids, IL-6, IL-1 inhibitors, and anti-TNF and Janus Kinase (JAK) inhibitors." (PMID 36226148, 2022). "As a pleiotropic cytokine, IL-6 plays an important role as an inducer of hepatic acute phase responses, and one of the cytokine-targeted approaches for severe COVID-19 includes IL-6 blockade, however with modest clinical benefit." (PMID 35743825, 2022). "Higher IL-6 but lower IL-1α levels have been detected in patients with primary COVID-19 compared to influenza." (PMID 36430430, 2022). "Randomized controlled clinical trials with agents targeting the IL-6 signalling in COVID-19 that are ongoing or awaiting results (as reported in Clinicaltrials.gov; last accessed December 6, 2021)." (PMID 35340805, 2022). "Compared to patients with moderate symptoms, patients with severe COVID-19 symptoms express high levels of inflammatory cytokines, such as IL-6." (PMID 35565841, 2022). "In fact, IL-6 after HD was reported to be elevated compared to that before HD in COVID-19 patients, especially in critical cases." (PMID 35615622, 2022). "This study will provide valuable insights on the use of colchicine in severe COVID-19 when added to IL-6 antagonists." (PMID 36181009, 2022). "Earlier studies have shown that increased levels of IL-6 are related to increased disease severity and resultant mortality in COVID-19." (PMID 36185918, 2022). "Elevated serum IL-6 levels have been documented in patients with COVID-19 and were related to the severity and poor prognosis of the disease." (PMID 36363785, 2022).
COVID-19 (continued). "The plasma level of vitamin D and IL6 (D low and IL6 high in COVID-19 patients; D high and IL6 low in healthy patients) and ABG were highly distinctive patterns between the COVID-19 and healthy groups." (PMID 36428884, 2022). "COVID-19 patients with DM and cardiac injury presented a decreased number of immunocyte subsets, lower C3 concentration, and a higher level of interleukin-6 (IL-6) and immunoglobulin A (IgA)." (PMID 36123740, 2022). "A previous study also suggested that IL-6 and IL-10 levels were significantly increased in patients with severe COVID-19 and were strong predictors of severe disease." (PMID 35687545, 2022). "IL-1 inhibitors (IV anakinra 2-10 mg/kg/dose - maximum 100 mg dose), IL-6 inhibitors (tocilizumab 4-8 mg/kg per dose), and convalescent plasma from recovered COVID-19 patients are tried." (PMID 35340456, 2022). "It is already known that cytokine storm (hypercytokinemia) resulting in increased systemic inflammation with high levels of IL-6, IL-1β, and TNFα is induced by viral infections, including influenza A and COVID-19." (PMID 36504633, 2022). "For example, the levels of IL-6 were shown in several studies to be the main contributor to the prognosis in COVID-19, but at the same time, the threshold of IL-6 levels differed in these trials significantly, with a range from 30 pg/mL to 163.4 pg/mL." (PMID 35887283, 2022). "We characterized the relationship between the proinflammatory cytokine IL-6 and T, B, NK, and Treg lymphocyte subsets in the blood samples of 125 COVID-19 patients at inpatient admission." (PMID 36403042, 2022). "Over the past few months, the role and importance of IL-6 in COVID-19 have been intensively studied." (PMID 35464749, 2022). "These clinical laboratory test items include interleukins 6 (IL-6) and 10 (IL-10) and serum ferritin which all potential aid in predicting severe and fatal COVID-19 were identified." (PMID 36153474, 2022). "Steroids use for COVID-19, anti-IL6 or anti-IL6R treatment and admission to ICU were more common among patients who developed thrombosis in contrast to patients who did not develop thrombosis." (PMID 36028857, 2022). "The other PI3K/AKT signaling pathway stimuli which have been increased in COVID-19 patients are inflammatory cytokines, including IL-6, IL-1, TGF-β, and TNF-α." (PMID 35016612, 2022). "IL-6, in particular, activates the pathway that leads to cellular apoptosis of the olfactory epithelium; it has been shown that a decrease in IL-6 levels favors the recovery of smell after post-COVID-19 anosmia." (PMID 35269410, 2022). "This becomes more evident when evaluating predictive markers of lethal COVID-19, which yields IL-6 and lymphocyte (percentage of total WBC) as the only two significantly predictive markers shared in both male and female patients." (PMID 35351135, 2022). "In the case of COVID-19, patients who have an excessive inflammatory response are treated with monoclonal antibodies that neutralize inflammatory cytokines such as IL-6, or therapy that removes inflammatory factors in the blood through apheresis." (PMID 36365041, 2022). "Meanwhile, the concentration of IL-6 in severe COVID-19 and death group was 1,463 and 2,200 pg/ml, respectively." (PMID 35784318, 2022). "Laboratory abnormalities observed in adults, including elevated levels of D-dimers and cytokines (IL-6, IL-10, TNF-alpha), have been associated with severe COVID-19 courses and increased mortality." (PMID 35546159, 2022). "Interleukin 6 (IL-6) is one of the most recognized factors of the inflammatory responses; its role in COVID-19 has been extensively studied in recent years." (PMID 36430621, 2022). "Their results show a higher incidence of severe and even fatal forms of COVID-19 when IL-6 and IL-10 are high." (PMID 35874678, 2022).
COVID-19 (continued). "Increased levels of IL-6 and C-reactive protein (CRP) are associated with a worse outcome from COVID-19, suggesting that inflammation contributes as a critical mediator to the heightened mortality of those patients." (PMID 35359931, 2022). "Findings of our study reinforce the role of IL-6 as an important prognostic marker in severe COVID-19." (PMID 36366295, 2022). "According to the previous studies, levels of the disease progression indicators CRP, PCT, IL-6, and D-dimer are found to be significantly higher in COVID-19 patients with hypocalcemia." (PMID 35678023, 2022). "Studies that identified COVID-19 predictors of severe illness and high mortality rates reported elevated IL-6 levels among deceased cases compared to survivors." (PMID 35203844, 2022). "The most predictive biomarker for COVID-19 complications IL-6 was found 10 times decreased by the beginning of the trial (at the 30th–40th days after discharge from the hospital) as compare to its plasma content at the admission to the hospital." (PMID 35684003, 2022). "In COVID-19 patients, elevated serum levels of IL-6, IL-1β, TNF- α, IL-10, and CRP have been measured and discussed." (PMID 36268187, 2022). "Other therapeutic approaches in COVID-19 involve the use of biologics that target pro-inflammatory cytokines, such as IL-6, IL-1, GM-CSF, and TNFα." (PMID 36341409, 2022). "A variety of cytokines, including IL-6, are involved in severe COVID-19, and anti-inflammatory treatment is of great significance in the protection of severe patients." (PMID 36506506, 2022). "The immune response in COVID-19 is characterized by increased secretion of pro-inflammatory cytokines, and interleukin 6, one of the major pro-inflammatory cytokines, has been proposed to be a marker of severity in COVID-19 patients." (PMID 35563870, 2022). "Once IL-6 is released, it not only induces apoptosis pathway and excessive exhaustion of T cells in server COVID-19 patients, but also plays a pathological role in chronic inflammatory disease (including cardiovascular disease) after SARS-CoV-2 infection." (PMID 36123740, 2022). "Flow cytometry based study on monocytes from patients with severe COVID-19 demonstrated elevated levels of IL-6, IL-1, and TNF-α, indicating an inflammatory monocyte phenotype." (PMID 35601440, 2022). "Currently, host response biomarkers used for predicting COVID-19 severity include proinflammatory cytokines (IL6, TNF, IL8, etc.), inflammatory markers (CRP, procalcitonin, and ferritin, etc.), neutrophil/lymphocyte ratio, and lymphopenia." (PMID 36741372, 2022). "The cytokine IL-6 contributes to hyper-inflammation and its levels strongly correlate with the severity of COVID-19." (PMID 36398441, 2022). "The most relevant results are that resistin, IL-6, IL-8, IL-15, IL-18, MCP-1 and TNF-α are the main cytokines associated to COVID-19 symptomatology; meanwhile resistin, IL-8, IL-15, MCP-1 and TNF-α used to be associated with oxygen therapy necessity." (PMID 35330391, 2022). "Both COVID-19 and PE are connected to hypocalcemia, elevated lactate dehydrogenase and sFlt1, hypoalbuminemia, elevated levels of IL-6 and D-dimer, thrombocytopenia, and proteinuria." (PMID 36431122, 2022). "Here, serum cytokines such as IP-10, MCP-1, MIP-1α, and IL-6 play a major role in determining COVID-19 disease severity." (PMID 35822078, 2022). "Although several factors, including elevated levels of inflammation markers such as C-reactive protein (CRP) and interleukin-6 (IL-6) correlate with severity of COVID-19, the course of severe disease remains highly unpredictable." (PMID 36171547, 2022). "Raised interleukin-6 levels in COVID-19 further increase free iron level through increased production of ferritin." (PMID 35155019, 2022). "Tocilizumab, a specific monoclonal antibody that blocks IL-6, has been recommended for use in critically ill COVID-19 patients with extensive bilateral pulmonary lesions and with elevated serum levels of IL-6." (PMID 35222441, 2022).
COVID-19 (continued). "At present, a number of clinical studies have been carried out to down-regulate the levels of inflammatory factors in patients with COVID-19, including monoclonal antibodies against IL-6 and IL-1β, and inhibitors of JAK-STAT signaling pathway." (PMID 35935817, 2022). "In our study, IL-6 and IL-6/Ly have a predictive value for the mortality of critically-ill patients diagnosed with COVID-19." (PMID 36142336, 2022). "In stage III of COVID-19 patients, moderate positive correlation was noticed between Gal-1 and IL-1β (p = 0.001) and IL6 (p = 0.005) and strong positive correlation between Gal-1 and IL-10 (p = 0.001), IL-23 (p = 0.001) and IL-33 (p = 0.001)." (PMID 35075140, 2022). "The survival rate was increased in ill COVID-19 patients with comorbidities, and IL-6 was significantly decreased in recovered patients." (PMID 35287354, 2022). "On the other hand, Rapamycin is widely used as inhibitor of protein synthesis and constrains the expression of pro-inflammatory cytokines such as IL-2, IL-6 and, IL-10116, therefore it has been also given for COVID-19 treatment." (PMID 35277538, 2022). "New reliability and output data on IL-6 and IL-6R targeting will emerge to implement more individualized therapies that work better to control the systemic impact of COVID-19." (PMID 35457086, 2022). "A meta-analysis of RCTs reported a decreased incidence of death in COVID-19 patients receiving IL-6 inhibitors." (PMID 35215138, 2022). "Low 25-hydroxy vitamin-D (25-OH D) levels are correlated with high IL-6 levels, and were found to be independent predictors of COVID-19 severity and mortality in the general population." (PMID 35053983, 2022). "NK cells also react to and generate cytokines such as IL-12 and IL-2, as well as IFNg, TNFa, and IL-6, with all these cytokines being amplified in the COVID-19 cytokine storm." (PMID 35669157, 2022). "In COVID-19 patients, increased levels of IL-6 are recorded, especially in patients with a severe-to-critical form of the disease, and an increasing mean in IL‐6 on admission was associated with an increased likelihood of mortality." (PMID 35873360, 2022). "High levels of IL-6 correlate with a lower number of NK cells in COVID-19 patients, whereas a decrease in NK cell frequency correlates with COVID-19 disease severity." (PMID 35891232, 2022). "The majority of upregulated cytokines and chemokines, such as IL-6, TNF, CCL2, CCL3, and CXCL10, have been reported to be associated with cytokine release syndrome (CRS), including MAS, in severe COVID-19 cases." (PMID 35440562, 2022). "This research also showed that, out of thirteen targets, the top six (IL-6, PPARG, MAPK3, PTGS2, ICAM1, and MAPK1) are likely to be implicated in the anti-COVID-19 effects of Kochiae Fructus’ active phytomolecules." (PMID 35992697, 2022). "In suspected or confirmed patients of COVID-19, all biological DMARDs (bDMARDs) besides IL-6 inhibitors, as well as all targeted synthetic DMARDs (tsDMARDs), should be ceased." (PMID 35054471, 2022). "Fibrotic manifestations resulting from lung injury 49, 50 are commonly associated with severe injury, and some of the molecular markers, such as TGF-β and IL-6, are increased in the peripheral blood of severe COVID-19 patients." (PMID 36147459, 2022). "In the case of COVID-19, the production of inflammatory cytokines such as IL-6, IL-1, TNF-α, and CRP contributed to a storm of cytokines resulting in an immune dysregulation induced by T cells and inflammatory monocytes." (PMID 35685606, 2022). "A key role of interleukin-6 (IL-6) in the pathogenesis of taste disorder in COVID-19 patients has been highlighted." (PMID 36501098, 2022). "Given that high IL-6 levels were observed in patients with severe COVID-19, IL-6 receptors are a target in COVID-19 treatment." (PMID 35565831, 2022).